VDAC1 (voltage dependent anion channel 1)
Diseases named in the same sentence as VDAC1 in open-access papers (continued):
Sharing a sentence is not in itself a finding about the gene and the disease.
cancer (continued). "Our results suggest that depletion of VDAC1, serving as the bottleneck between mitochondrial and cellular metabolism, can be considered a novel strategy to target various cancers." (PMID 31195298, 2019). "In other words, VDAC1 depletion in tumor cells of human origin resulted in a global change in cancer cell metabolism, with these metabolic changes affecting the expression of genes associated with the microenvironment of mouse and human cells in the tumor." (PMID 31661894, 2019). "An increased expression of VDAC1 sensitizes cancer cells to anti-cancer drugs via Ca2+-dependent mechanism." (PMID 31226817, 2019). "VDAC1 is highly expressed in different tumors, pointing to its pivotal role in regulating cancer cell energy and metabolism." (PMID 31195298, 2019). "Inhibition of these pathways and more downstream targets, such as glucose transporters, glycolytic (iso)enzymes, or the mitochondrial pore (VDAC1), provides a tempting avenue for the development of new anti-cancer drugs." (PMID 31803611, 2019). "The significance of VDAC1 for cancer cell viability is underscored by results showing that abrogation of VDAC1 expression reduced cellular ATP levels, tumor development and growth." (PMID 31661894, 2019). "As such, VDAC1 is highly expressed in various tumors obtained from patients or produced in mouse models, pointing to its pivotal role in regulating cancer cellular energy and metabolism." (PMID 31661894, 2019). "In our previous study, several novel VDAC1 N-terminal-derived peptides were designed and tested for their ability to induce cell death in cancer cells." (PMID 31474832, 2019). "The use of si-RNA specific to human VDAC1 allows for evaluating crosstalk between cancer cells and the tumor microenvironment." (PMID 31661894, 2019). "VDAC1, a protein that regulates cell metabolism, is highly expressed in various cancers, including GBM, pointing to its important function in cancer development and survival." (PMID 31661894, 2019). "Given that VDAC1 depletion rewires cancer cell metabolism and reverses cancer cell properties to normal-like cells, the decrease in activated AMPK levels is expected." (PMID 31195298, 2019). "In general, both short- and long-term treatment with si-hVDAC1 similarly reduced the expression of metabolism-related enzymes, pointing to VDAC1 depletion in cancer cells reversing their reprogramed metabolism." (PMID 31661894, 2019). "Consistent with this, patients whose carcinomas expressed VDAC1 at low to moderate levels had significantly reduced survival compared to high expressors (p < 0.05)." (PMID 31167495, 2019). "Our findings point to VDAC1 as a significant control point for reprogramming metabolism, reversing the properties of cancer cells and thus, representing an emerging cancer drug target." (PMID 30544833, 2018). "The level of VDAC1, a key protein in cancer cell energy and metabolism homeostasis, was also decreased, as were the levels of the Krebs cycle enzyme citrate synthase (CS), the electron transport chain protein complex IV, and ATP synthase subunit 5a." (PMID 29698587, 2018). "Various anti-cancer molecules are able to directly or indirectly target to VDACs (in particular VDAC1 isoform)." (PMID 30011966, 2018). "This concept is further backed by studies showing that down-regulation of VDAC1 expression led to reduced metabolite exchange between mitochondria and the cytosol and inhibition of the growth of various cancer cell types and tumours." (PMID 30544833, 2018). "It is proposed thatmodifications in mitochondrial dynamics and production of VDAC1-ΔC are a survivalresponse in hypoxic cancer cells that resist apoptosis." (PMID 29560113, 2018). "We found out that specific depletion of this protein also induced the accumulation of VDAC1-ΔC, implying that CISD2 plays a pivotal role in the fate of VDAC1, a potential mitochondrial marker for cancer severity and prognosis." (PMID 29596470, 2018).
cancer (continued). "VDAC1 contributes to the phenotype of cancer cells, regulating cellular energy production and metabolism." (PMID 29593233, 2018). "Our results are the first to associate dysfunction in Fe-S cluster biogenesis with cleavage of VDAC1, a form which has previously been shown to promote tumor resistance to chemotherapy, and raise new perspectives for targets in cancer therapy." (PMID 29596470, 2018). "The voltage-dependent anion channel (VDAC1), serving as the mitochondria gatekeeper, can equally be considered as a target in tackling the altered metabolism of cancer cells." (PMID 30544833, 2018). "Cancer cell metabolism in culture or in tumour can be targeted by reducing the expression of the mitochondrial gatekeeper VDAC1 using specific siRNA, reversing cellular oncogenic properties." (PMID 30544833, 2018). "Upon VDAC1 depletion, cancer cell energy and metabolic homeostasis are impaired, leading to de-programming of cancer cell energy and metabolism, involving changes in the expression of the TFs and genes associated with metabolic regulation." (PMID 30544833, 2018). "VDAC1 is highly expressed in various tumours, which points to its crucial role in the metabolic and survival pathways of cancer cells." (PMID 30544833, 2018). "Metabolic reprogramming of cancer cell via VDAC1 depletion highly reduced CSC markers, the result of inhibition of CSC proliferation and/or due to the induction of differentiation." (PMID 30544833, 2018). "For instance, VDAC1 expression levels are correlated with tumor growth and invasion in several types of cancer, e.g. non-small cell lung cancer and cervical cancer." (PMID 29491433, 2018). "In this review, we grouped molecules that, by acting on VDAC1, exert pro- and anti-apoptotic features, thus putatively able to counteract mitochondrial dysfunction in cancer and neurodegenerative diseases, respectively." (PMID 29682501, 2018). "VDAC was proposed as the pharmacological target of FNQs, since their anti-cancer activity was increased upon VDAC1 overexpression and decreased upon VDAC1 silencing by siRNA." (PMID 29682501, 2018). "Together, the data presented here support the suggestion that VDAC1 depletion in cancer cells leads to metabolic reprogramming, which via different molecular processes mediated by TFs and epigenetics, directed the tumour cells to more differentiated stages." (PMID 30544833, 2018). "In this regard, recently, genetic disruption of VDAC1 in cells from cancer xenograft models displayed decreased mitochondrial membrane potential and ATP content with a consequent low migration rate and tumor regression." (PMID 29491433, 2018). "Taken together, these findings indicate a similar reversal of the metabolic reprogramming of cancer cells in the three tumour types that were tested upon silencing VDAC1 expression." (PMID 30544833, 2018). "We have shown in a previous study with GBM that silencing VDAC1 expression in tumours led to cancer-reprogrammed metabolism." (PMID 30544833, 2018). "As such, VDAC1 is involved in two important hallmarks of cancer development, namely energy and metabolic reprograming and apoptotic cell death evasion." (PMID 29698587, 2018). "As a transporter of metabolites, VDAC1 controls cell energy and metabolic homeostasis, is over-expressed in many cancers and contributes to the metabolic phenotype of cancer cells." (PMID 30544833, 2018). "Since altogether the OXPHOS complexes and VDAC1 are increased in carcinomas, we conclude that mitochondrial mass is higher in carcinomas than in benign prostate tissue." (PMID 30538797, 2018). "On the other hand, disruption of VDAC1-HK-interaction by the peptides presented here provides a strategy to interfere with cancer cell growth and activate apoptosis and can thus be considered as a promising approach for cancer therapy." (PMID 28412744, 2017).
cancer (continued). "Modulating VDAC1 expression levels or its apoptotic activity are possible strategies to either activate apoptosis in cancer or inhibit apoptosis in CVDs, AD and T2D." (PMID 30542671, 2017). "The first strategy involves modification of cell metabolism using VDAC1-specific small interfering RNA leading to inhibition of cancer cell and tumor growth and reversed oncogenic properties." (PMID 28824871, 2017). "The function of VDAC1 in energy metabolism of cancer cells and the significance of the overexpression in many cancer cells is discussed further below (see VDAC1 Expression Level and Cell Death Induction—a New Concept, Unraveling VDAC1-Based Therapies)." (PMID 28824871, 2017). "We found that the level of the mitochondrial gatekeeper protein, VDAC1, was substantially higher in different cancer types, in comparison to healthy tissues." (PMID 29285267, 2017). "This novel mechanism provides a platform for developing a new class of drugs to treat cancer acting via modulating VDAC1 levels through action on the gene promoter." (PMID 28824871, 2017). "VDAC1 overexpression is, moreover, a signature of most cancers and can serve as a prognostic biomarker to predict clinical outcome in diversified human cancers." (PMID 28824871, 2017). "As already discussed, VDAC1 offers a unique target for anti-cancer therapies because of its role as a key regulator of energy and metabolism and apoptosis." (PMID 28824871, 2017). "Voltage-dependent anion channel 1 is highly expressed in many cancer types compared to the levels in normal cells." (PMID 28824871, 2017). "Since VDAC1-bound HK is essential for tumor cells, the detachment of HK from VDAC1 represents a novel therapeutic strategy to impair cancer metabolism and augment apoptosis." (PMID 28824871, 2017). "Despite these concerns, targeting VDAC1–HK interaction proposed as a promising target for anti-cancer therapy." (PMID 28824871, 2017). "VDAC1-based peptides, expecting to also affect other cancers, provide the opportunity for the development of new anti-cancer therapies that will allow overcoming the chemo-resistance of cancer cells." (PMID 30542671, 2017). "Recently, synthetic VDAC1-based peptides were shown to interact directly with HK-I and HK-II and lead to their dissociation from VDAC1 (see VDAC1-Based Peptides As Potential Anti-Cancer Therapy)." (PMID 28824871, 2017). "This proposal is based on the observation that several cancer drugs and treatments induce apoptosis as well as upregulating VDAC1 expression levels." (PMID 28824871, 2017). "Interaction of HK-II and VDAC1 provides metabolic advantage to the cancer cells by strengthening anaerobic glycolysis." (PMID 28327594, 2017). "As already discussed, VDAC1 is overexpressed in many cancer types (see Alterations in VDAC1 Expression Level in Cancer) and, thus, presents anchoring sites for overexpressed HK, allowing direct access to mitochondrial ATP and an increased glycolytic rate." (PMID 28824871, 2017). "Down-regulation of VDAC1 addresses the cancer trademark of cell metabolic and energy reprogramming, leading to disrupted cancer cell energy and metabolism homeostasis." (PMID 30542671, 2017). "The over-expression of VDAC1 in cancer 54, 59, in affected regions of AD brains 97, 98, 99, in β-cells of T2D 101 and in CVDs 250, is a feature common to these diseases." (PMID 30542671, 2017). "VDAC1 also regulates apoptosis via binding of apoptosis-regulating proteins, such as HK, Bcl-2 and Bcl-xL, some of which are also highly expressed in many cancers." (PMID 28412744, 2017). "Finally, VDAC1 silencing in tumors leads to reprogramed metabolism and results in alterations in the transcription factors that regulate signaling pathways associated with cancer hallmarks affecting angiogenesis, EMT, invasiveness, stemness, and induced differentiation." (PMID 28824871, 2017).
cancer (continued). "In summary, VDAC1 functions in ATP production and metabolism, Ca2+ homeostasis and apoptosis execution are indispensable for proper mitochondrial function of cancer cell, and consequently, for cell activity." (PMID 30542671, 2017). "VDAC1, standing at the crossroads between mitochondrial-mediated energy and metabolism and apoptosis, is a potential target for treating cancer and other diseases involving dysregulated metabolism and/or apoptosis and where VDAC1 is over-expressed." (PMID 30542671, 2017). "As cellular metabolic and energy reprogramming are cancer hallmarks essential for tumor progression, and VDAC1 is a key regulator of these processes 1, 30, 32, 47, 52, 89, down-regulation of VDAC1 expression is expected to impact cancer cell growth." (PMID 30542671, 2017). "In this study, we targeted the cancer hallmarks of reprogrammed metabolism and apoptosis avoidance using voltage-dependent anion channel 1 (VDAC1)-based cell-penetrating peptides." (PMID 28412744, 2017). "Silencing VDAC1 expression by a single siRNA specific to the human VDAC1 (si-hVDAC1) sequence resulted in cell proliferation and cancer cell growth inhibition both in cell cultures and in vivo animal models." (PMID 28824871, 2017). "As a mitochondrial gatekeeper and overexpressed in cancer VDAC1 is a very attractive emerging anti-cancer drug target." (PMID 28824871, 2017). "Expression of the VDAC1 isoform is robustly increased in many cancer cell types and reliably predicts survival outcomes in breast, colon, and lung cancers." (PMID 28848710, 2017). "DIDS, SITS, H2DIDS, DNDS, and DPC, which are known anion transport inhibitors, all interact with VDAC1, and inhibit apoptosis stimuli-induced apoptosis and VDAC1 oligomerization in many cancer cell lines." (PMID 28824871, 2017). "Recently, VDAC1, a voltage-dependent anion channel, contributes to the metabolic phenotype of cancer cells regulating mitochondrial activity and glucose metabolism." (PMID 28512624, 2017). "VDAC1 is now well-accepted as an important player in apoptosis and is being explored as a new target for cancer therapy." (PMID 28824871, 2017). "Strategically located in a “bottleneck” position, controlling metabolic homeostasis and apoptosis, VDAC1 thus represents an emerging target for anti-cancer drugs." (PMID 28824871, 2017). "This suggests that VDAC1 plays a key role in cancer cell fate by controlling the cross-talk between metabolism and oncogenic signaling networks, most likely affecting the interplay between metabolism and epigenetics." (PMID 28824871, 2017). "By regulating the metabolic and energetic functions of mitochondria, VDAC1 can, therefore, control the fate of cancer cells." (PMID 28824871, 2017). "VDAC1 is over-expressed in a variety cancer types, including GBM, suggesting its important metabolic function in the growth of cancer cells." (PMID 28412744, 2017). "VDAC1 can thus be considered as standing at the crossroads between mitochondrial metabolite transport and apoptosis and hence represents an emerging cancer drug target." (PMID 30542671, 2017). "On the outer membrane of mitochondria, HK-2 interacts with VDAC-1 to form complex to prevent cancer cell apoptosis." (PMID 28320429, 2017). "Targeting VDAC1, acting as a ‘governor’ of mitochondrial function, regulating cellular energy and metabolism, and over-expressed in cancer, offers a unique target for anti-cancer therapies." (PMID 30542671, 2017). "As a transporter of metabolites and Ca2+, VDAC1 contributes to the metabolic phenotype of cancer cells, possibly as reflected in its overexpression in many cancer types." (PMID 28443244, 2017). "In cancer cells, high free tubulin inhibits VDAC1 and VDAC2, contributing to suppression of mitochondrial function in the Warburg phenomenon." (PMID 29312883, 2017). "Other potential cancer-fighting agents also appear to target VDAC1 directly to alter its channel's gating properties." (PMID 28713289, 2017).
cancer (continued). "The role of VDAC1 as a key regulator of the cellular metabolic and energy reprogramming processes essential to cancer survival makes targeting VDAC1 an attractive strategy for anti-cancer therapy." (PMID 28824871, 2017). "Anticancer, pro-apoptotic drugs, and chemical agents that increase voltage-dependent anion channel 1 expression level in cancer cells." (PMID 28443244, 2017). "Experimental evidence using single and double knockdown of VDAC1/2/3 showed that VDAC regulates mitochondrial metabolism in cancer cells as determined by mitochondrial ΔΨ, ATP production, and NADH generation." (PMID 28168164, 2017). "The findings presented above suggest that modulating VDAC1 expression levels or its apoptotic activity are possible strategies to either activate apoptosis in cancer or inhibit apoptosis in CVDs, AD and T2D." (PMID 30542671, 2017). "Overexpressed VDAC1 presents anchoring sites for the cancer overexpressed HK and for Bcl-2 and Bcl-xL, interactions that are important for their anti-apoptotic activities (see Modulation of VDAC1-Mediated Apoptosis and Metabolism VIA Interacting Proteins)." (PMID 28824871, 2017). "In cancer cells, over-expressed anti-apoptotic proteins interact with VDAC1, thereby preventing VDAC1 pro-apoptotic activity." (PMID 27078856, 2016). "Consistent with previous studies in other cancers, VDAC1 mRNA levels were significantly increased in NSCLC tissues versus adjacent non-tumor tissues." (PMID 27304056, 2016). "Strong VDAC1 expression was observed in cancer cells, degenerate acinar cells, while various intensities of VDAC1 positivity were observed in cancer cells from the PDAC tissue samples." (PMID 27659305, 2016). "As it functions at the crossroads of metabolic and survival pathways, VDAC1 seemed to be a promising mitochondrial target for cancer therapy." (PMID 27419626, 2016). "Although it seems surprising not to find VDACs in a tissue, we recently reported, using the Cancer Genome Atlas (TCGA) data sets from 89 cancer studies, that deletion of the VDAC1 gene is found in some cancer types." (PMID 27625993, 2016). "Only four cancer tissues (22.2%) showed higher VDAC1 expression, while 17 cancer tissues (94.4%) showed higher MTDH expression." (PMID 27229534, 2016). "A second group of proteins associated with metabolism and apoptosis, including VDAC1, VDAC2 and AIF, were reported for some cancers other than CLL (group B)." (PMID 27078856, 2016). "VDAC1 is an important target for cancer therapies and some small molecule drugs were found to target the upregulation of VDAC1, as prednisolone, cisplatin, or arbutin in different cancer cell lines." (PMID 27589771, 2016). "The PTP is composed of or activated by VDAC1, adenine nucleotide translocase and cyclophilin in cancer cells." (PMID 26716410, 2016). "Our previous experiment, using genechips, revealed that human nonmetastatic clone 23 type 1 (nm23-H1) has decreased the expression of voltage-dependent anion channel 1 (VDAC1) in cancer cells of the uterine cervix." (PMID 26716410, 2016). "As a transporter of metabolites, VDAC1 contributes to the metabolic phenotype of cancer cells such as increased proliferation and invasiveness." (PMID 27304056, 2016). "In summary, the exposure of HT-29 carcinoma cells to hierridin B induced significant changes in VDAC1 mRNA expression and protein content." (PMID 27589771, 2016). "Cells with enlarged mitochondria and cleaved VDAC1 were also more resistant to chemotherapy-stimulated cell death than normoxic cancer cells." (PMID 26322231, 2015). "The results of the present study reveal that the role of VDAC1 in cancer is connected to modulation of energy and cell death, which are closely interconnected." (PMID 26322231, 2015). "VDAC1-ΔC was present in cancer cell lines that had high-cytoplasmic levels of adenosine triphosphate and in lung cancer biopsies that showed a strong resistance to chemotherapy-induced apoptosis." (PMID 26090338, 2015).